IL2 (interleukin 2)
Diseases named in the same sentence as IL2 in open-access papers (continued):
Sharing a sentence is not in itself a finding about the gene and the disease.
cancer (continued). "Recognition of these cognate cancer‐specific antigens by the engineered antibodies causes to initiation of some signaling pathways in T cells that induce production of several pro‐inflammatory cytokines (IFN‐γ, TNF‐α, IL‐6, and IL‐2) and cytolysis (osmotic lysis) of cancer cells." (PMID 36583504, 2023). "TVA was ranked top and was further confirmed to enhance IL-2 production from mouse and human primary T cells and rescue PD-L1–PD-1-dependent exhaustion of Jurkat T cells induced by co-cultured PD-L1-expressing human cancer cells, as indicated by reversed inhibition of IL-2 production." (PMID 37993715, 2023). "The differential readout of NK cell viability was further employed to demonstrate that the administration of cytokines (e.g., IL-2, IL-15, and IL-21) improved the in vivo survival of NK cells and led to better anti-cancer outcomes in a mouse model of hepatocellular carcinoma." (PMID 37376918, 2023). "The therapeutic potential of IL-2 has also been recognized in the field of cancer immunotherapy." (PMID 37516849, 2023). "Furthermore, authors accessed also other prevalent inflammation and cancer cytokines such as IL-1β, IL-2, and IFN-γ, which were overexpressed in TME." (PMID 37958406, 2023). "For instance, interleukin-2 (IL-2) and interferon-alpha (IFN-a), which are produced by T-lymphocytes and leukocytes, respectively, have been used clinically in the recombinant form for cancer management, and both have been associated with cardiotoxicity." (PMID 37355743, 2023). "However, the TME's primary cytotoxic γδ T cell promoters, IL-2 and IL-15, are crucial for regulating cytotoxic γδ T cells in cancer immunotherapy." (PMID 37841886, 2023). "A summary of IL-2-based therapies used for cancer treatment follows." (PMID 36936961, 2023). "Immune checkpoint inhibitors have now received FDA approval for first- and second-line treatment for various cancers, and favorable effectiveness has been seen in patients with metastasis and recurrence, such as the cytokines interferon-alpha, the interleukin-2 (IL-2)." (PMID 36969161, 2023). "In addition, research has demonstrated that various cancer types exhibit different levels of IL-2 and IL-2R expression, which can impact their response to immunotherapy." (PMID 37516849, 2023). "Since the discovery of interleukin-2 (IL-2) in 1976 as a potent growth factor promoting the expansion and maintenance of function of human T cells, there has been great interest in harnessing its pleotropic activities against cancer." (PMID 37174716, 2023). "TANs provide a favorable environment for cancer development, angiogenesis and metastatic spread by secreting cytokines and chemokines, such as interleukin-2 (IL-2), interleukin-6 (IL-6), interleukin-10 (IL-10), tumor necrosis factor α (TNF-α) and vascular endothelial growth factor (VEGF)." (PMID 36661728, 2023). "Interleukin-2 (IL-2) is a cytokine playing an important role in cancer immunotherapy." (PMID 36794182, 2023). "IL‐2‐induced Treg cell expansion has been a major drawback for IL‐2‐based cancer immunotherapies." (PMID 36684086, 2023). "Thus, we show here that IL-2 with IL-12 is a rational combination for systemic cytokine-based immunotherapy of cancer and that the dose-limiting toxicity of this combination can be overcome by protein engineering approaches." (PMID 37669107, 2023). "Immunostimulatory agents such as recombinant cytokines (INF-α, IL-2) used in the treatment of cancer have adverse consequences, including the acute phase response, cell and tissue abnormalities/injury, cytokine release/cytokine storm, tumor lysis syndrome, vascular leak, and autoimmunity." (PMID 37046608, 2023). "Interleukin-2 (IL-2) is a widely recognized cytokine that holds a significant role in the growth and proliferation of various immune cells Notably, IL-2 has emerged as a crucial immunotherapy cytokine for treating diverse conditions, including cancer." (PMID 38022554, 2023).
cancer (continued). "Determining how IL-2 therapy can be used to suppress TEX while attenuating its effects on Treg expansion may help in modulating T-cell exhaustion in cancer." (PMID 36891319, 2023). "IL-2 is used to stimulate T cell production for enhancing anti-cancer immunity." (PMID 37237491, 2023). "IL18 in combination with IL2 induces NK cells and has a cytotoxic role against cancers." (PMID 38139000, 2023). "As we have shown that co-expression of flNFAT2 increases IL2 secretion in Jurkat cells, we were wondering if this could correspond with augmented cancer killing in human CD19 CAR-T cells." (PMID 37223115, 2023). "Furthermore, the efficacy of IL-2 and IL-2R-targeted therapies is limited in particular cancer types, such as breast or lung cancer." (PMID 37516849, 2023). "In addition, TGFβ-stimulated CAFs have been a suggested target to treat unresponsive tumors restoring trastuzumab anti-cancer efficiency through increased IL-2 production." (PMID 36940196, 2023). "In the cancer context, CD158b upregulation has been negatively associated with NK cell activation and production of CD107, IFN-γ, and perforin even when tumors are exposed to exogenous IL-2 and IL-15 cytokines." (PMID 37949944, 2023). "Taken together, it became obvious that much more effective and much faster GvL-like anti-cancer effects could be induced by transient circulation of IL-2 preactivated intentionally mismatched killer cells consisting of a mixture of both T and NK cells." (PMID 37202579, 2023). "In addition, IL-2 and IL-2R have also been found to play a significant role in the development and progression of cancer." (PMID 37516849, 2023). "IL-2 has been shown to activate T cells, which can then target and kill cancer cells, while IL-2R is expressed on the surface of certain immune cells, such as natural killer (NK) cells, and can help to stimulate these cells to fight cancer." (PMID 37516849, 2023). "IL-2 plays a crucial role in T cells’ growth and differentiation, and it is often used in cancer immunotherapy to amplify the immune system’s capacity to fight cancer, mainly through promoting the proliferation and activation of CTLs and NK cells." (PMID 37895855, 2023). "Furthermore, adoptive cell transfer (ACT) of orthogonal IL-2Rβ transduced effector CD4 + and CD8 + T cells resulted in elevated anti-tumor immune responses upon orthogonal IL-2 injection in a pre-clinical cancer model." (PMID 36562079, 2023). "Considering their clinical potential and the early successful use of cytokines in cancer immunotherapy, such as interferon alpha-2b (IFNα-2b; IntronA®) and IL-2 (Proleukin®), cytokine-based therapeutics have been extensively evaluated in many follow-up clinical trials." (PMID 37483629, 2023). "Furthermore, ongoing phase I/II clinical trials in a variety of human cancers are also being performed using IL-2-stimulated donor allogeneic NK cells." (PMID 36980527, 2023). "The MTD of targeted TNF is 5–10 times lower than that of targeted IL2 in mice and cancer patients." (PMID 37092450, 2023). "TNF-α and IL-2 have been shown to participate in both initiation and progression of cancer." (PMID 37296375, 2023). "The efficacy of IL-2 as a cancer immunotherapy has been evaluated in various clinical trials." (PMID 37516849, 2023). "We obtained PBMC from patients before and after receiving HD IL-2 for cancer treatment." (PMID 37737264, 2023). "After prolonged cancer cell antigen exposure, autocrine scFv PD-L1 antibody promoted the proliferation ability, cytotoxicity, and IL-2 and IFN-γ secretion of CD19.BBz.PD-L1 and Her2.BBz.PD-L1 CAR T cells, suggesting that autocrine scFv PD-L1 antibody can improve T cell functions." (PMID 36835603, 2023). "armed OVV with IL-2 to effectively modify the cancer-immune set point, and combination with an anti-PD-1/PD-L1 antibody could cure most late-stage tumors in mice." (PMID 38169820, 2023). "As for IL-2, the influence of GM-CSF in anti-cancer immunity is dose-dependent." (PMID 37869009, 2023).
cancer (continued). "Several studies demonstrate that extracorporeal stimulation of autologous Natural Killer (NK) cells with Interleukin-2 (IL-2) in conjunction with adoptive transfer and subcutaneous IL-2 infusions increased overall survival (OS) in a subset of patients with advanced cancers." (PMID 37799714, 2023). "Furthermore, how do the IL-2 and IL-2R expression variations among different cancer types influence the therapeutic response?" (PMID 37516849, 2023). "In conclusion, the co-administration of CU06-1004 and IL-2 shows promise for cancer treatment." (PMID 37711172, 2023). "Taken together, these results led us to conclude that γδ T cells could have a role in cancer development via IL-2 or IL-17." (PMID 35493488, 2022). "IL2-Smurf2 chimeric proteins may be developed in the future both as a promising targeted cancer therapy and as a treatment for several other pathologies involving uncontrolled expansion of activated T-cells overexpressing the IL2-R." (PMID 36612252, 2022). "Regarding this proposal, many novel studies have approved that some peptide-related drugs such as mifamurtide, tumor necrosis factor-alpha (TNF-α), interferon-γ (INF- γ), and interleukin-2 (IL-2) cure human diseases including cancer and are found to be more effective." (PMID 35223470, 2022). "The expansion of Tregs represents an undesirable stimulation of IL-2 in cancer immunotherapy." (PMID 36230665, 2022). "Human interleukin 2 (IL-2) has shown impressive results as a therapeutic agent for cancer." (PMID 36230665, 2022). "IL-2 was the most widely used cytokine as a vaccine adjuvant in cancer vaccines." (PMID 35967400, 2022). "Altogether, the advantages IL-15 has over IL-2 indicate that it could be a highly effective and safe cytokine for cancer therapy." (PMID 35806311, 2022). "Although IL-2-mediated cancer immunotherapy has been used in the clinic for many years, high dose IL‐2 promotes the proliferation of cytotoxic effector T cells, as well as Treg cells, which can suppress the activity of effector T cells and thereby limit their antitumor efficacy." (PMID 36387134, 2022). "Cancer vaccine, in combination with other immunotherapy-based approaches such as cytokine therapy, in particular, low dose IL-2 and IFN-α, may stimulate promising outcomes in RCC patients." (PMID 36510217, 2022). "High-dose IL-2 was approved by the FDA in 1992 for treatment of certain types of cancer." (PMID 35104808, 2022). "Other proinflammatory cytokines (TNF-alpha, IL-2, IL-12, etc.)are also of great interest as therapeutic targets for cancer that could be affected by M/A." (PMID 35158753, 2022). "Many studies have investigated the co-expression of one or more cytokines (such as IL-2, IL-7, IL-12, IL-15, IL-18, IL-21, and IL-23), or the combination of their receptors to generate gene-edited interleukin-armored immune cells against cancer." (PMID 35806311, 2022). "Interleukin-2 (IL-2) has been shown to stimulate in vitro the generation of cytotoxic T lymphocytes and of lymphokine-activated killer cells, both of which are involved in killing of cancer cells." (PMID 35099641, 2022). "Likewise, increased levels of IFN-γ were seen when IL-2+sAJ2 treated NK cells were cultured with either cancer patients’ or healthy individuals’ monocytes." (PMID 35203349, 2022). "Therefore, further research is required to better understand the complex biology of IL-2 to harness its utility as cancer immunotherapy." (PMID 36135216, 2022). "Low efficacy of IL-2 therapy in cancer patients is due to the short serum half-life, which requires administration of high doses of IL-2 (600,000 IU/kg; 0.037 mg/kg, every 8 h for a maximum of 14 doses) and consequently, severe toxicity and vascular leak syndrome can occur." (PMID 35354847, 2022). "Since IL-1β, TNF-α, and IFN-γ cytokines are believed to mediate cytotoxicity of IL-2 based immunotherapies, mutant IL-2 with reduced binding to the high-affinity IL-2R may be more effective and less toxic for cancer treatment." (PMID 35354847, 2022).
cancer (continued). "Indeed, only Interferon-alpha (IFN-α) and Interleukin-2 (IL-2) have been so far approved by the FDA for cancer treatment as monotherapy." (PMID 36077623, 2022). "Therefore, this study aimed to generate a double deleted recombinant OVV armed with the human IL2 gene and to determine its expression levels of human interleukin-2 (hIL2) as well as oncolytic effects in both human and murine cancer cell lines." (PMID 35799600, 2022). "Moreover, our bioinformatic analysis showed the pathways associated with the platelet-related targets of validated miRNAs identified pathways in cancer and IL-2 signaling as those most affected by all of the validated miRNAs." (PMID 35596173, 2022). "IL-2 and IL-7 have been well demonstrated to enhance the T cell responses, indicating the potential role of IL-2 in combination with IL-7 as adjuvants for cancer vaccines." (PMID 36389666, 2022). "In conclusion, this study indicated that the mutant IL-2 (K35A, E61A, and F42A) could be a promising agent for IL-2-based immunotherapy of cancer." (PMID 35354847, 2022). "However, IL-2-based cancer therapy is limited by strong Treg amplification owing to its high binding affinity to IL-2 receptor α (IL-2Rα) and its short half-life owing to its small molecular size." (PMID 36230665, 2022). "Evidence from studies employing these long-lived IL-2 analogs in combination with cancer vaccines provides a basis for the continued improvement of these combinatorial therapies to further enhance antitumor responses in mouse models and translate these therapies to human studies." (PMID 35651800, 2022). "The application of IL-2 for treating cancer is limited owing to its toxicity and short half-life." (PMID 36230665, 2022). "Among which, IL-2 is one of the first cytokines that has been studied in cancer treatment." (PMID 36679904, 2022). "The first cytokine to be used in the treatment of cancer was IL-2." (PMID 36135216, 2022). "Lunasin exhibits immunomodulatory activity against cancer, specifically through combining with cytokines interleukin-2 (IL-2) and interleukin-12 (IL-12); this combination has a synergistic effect that stimulates natural killer (NK) cells to enhance interferon gamma (IFNγ) production." (PMID 36076946, 2022). "Studies have found reduced circulating levels of TRP in cancer patients treated with IL-2 or IFN-α." (PMID 36570839, 2022). "However, data pertaining to the efficacy of these fusion proteins when used as cancer vaccine enhancers is limited to the IL-2/CD25 transdimers fusion protein." (PMID 35651800, 2022). "Another type of cancer immunotherapy is active immunotherapy, which involves administration of agents, such as interferons, interleukins (e.g., IL-2, IL15, and IL-12), vaccines, and genetically engineered T cells, to direct the immune system into taking an active role in attacking the cancer cells." (PMID 36297474, 2022). "The underlying pathophysiology is complicated, involving the suppression of monocytes, cytotoxic T cells, and NK cell activity, as well as the inhibition of interleukin-2(IL-2) production, whose roles are crucial in the process of cancer cell recognition and eradication." (PMID 36612096, 2022). "IL-2 is regarded as the first effective immunotherapy for the management of human cancer." (PMID 35962391, 2022). "One major obstacle for IL-2 cancer immunotherapy is the high expression of IL-2Rα on Treg cells." (PMID 35104810, 2022). "For IL-2, T cells when interacting with cancer cells A549 could secret 206.8 ng/mL IL-2, which was lower than the amount of IL-2 secreted when CAR-T cells interacted with A549 cells (433.2 ng/mL)." (PMID 34189144, 2021). "In addition to macrophages, the presence CD8+ T cells and CD4+ T helper 1 cells (TH1) and their secreted cytokines such as interleukin-2 (IL-2), and interferon-γ (IFN γ) are often associated with good prognosis in various cancer types." (PMID 34071280, 2021).
cancer (continued). "IL-2 is a cytokine approved by the US Food and Drug Administration for the treatment of cancer." (PMID 34563040, 2021). "Interestingly, this study provided an additional molecular explanation for the anti-cancer effects of interleukin 2 (IL-2) therapy." (PMID 34639141, 2021). "However, IL-2 has the propensity to amplify Tregs, representing a major barrier for IL-2-based cancer therapy." (PMID 34394124, 2021). "Shortly after IL-2 approval, checkpoint inhibitors moved to the forefront of cancer research." (PMID 34200997, 2021). "This CD122-selective IL-2 complex (IL-2c) is the focus of this commentary as several groups have previously shown the efficacy of IL-2c in multiple murine cancer models including B16/F10 melanoma, pancreatic cancer model, BCL1 leukemia, TRAMP-C1 sarcoma, and orthotopic bladder cancer." (PMID 36968176, 2021). "Similarly, IL2 has been reported to stimulate both NK cells and T cells, with authors suggesting a role in cancer immunotherapy." (PMID 34464407, 2021). "Researchers engineered a mutant form of IL-2 called “super-2” with increased binding affinity for IL-2Rβ, which avoided the interference of Treg cells and induced superior expansion as well as improved anti-cancer activities of NK cells." (PMID 34439285, 2021). "Specifically, IL2-Fc has been utilized in preclinical models to enhance the magnitude and duration of adaptive and innate immune responses that occur in viral infections and cancer." (PMID 34790830, 2021). "Thus, the addition of ZOL to cultures of PBMC along with interleukin-2 (IL-2) leads to a selective expansion of Vγ9Vδ2 T cells, which are in turn highly efficacious killers of cancer cells upon sensitization of cancer cells with ZOL." (PMID 34149689, 2021). "Meanwhile, understanding of the cellular immune mechanisms paved the way for using the T cell growth factor interleukin-2 (IL-2) to stimulate anti-cancer CD8+ cytotoxic T lymphocytes (CTLs) in cancer patients and to expand these CTLs in vitro for the purpose of adoptive cell therapy (ACT)." (PMID 33671123, 2021). "Activation of the IL2/IL-2R axis is associated with the JAK-STAT signaling pathway, which may be related to cancer development as well as potential applications in cancer immunotherapy." (PMID 33625532, 2021). "Clinical trials will be necessary to explore the utility of IL2-Fc for the treatment of cancer." (PMID 34790830, 2021). "IL-2 is the prototypical cytokine employed as a cancer immunotherapeutic agent." (PMID 33671252, 2021). "Finally, the "IL-2 paradox" was recognized when patients were treated for a prolonged period with IL-2 often exhibited T cells anergy and cancer progression, rather than T cell activation and proliferation and consequently—cancer elimination." (PMID 33828163, 2021). "Due to this property, AnnV-IL2 has potential utility in cancer immunotherapeutic strategies and may be a feasible alternative to traditional IL-2 therapy." (PMID 34804041, 2021). "The interleukin-2 infusion can also be used to treat cancer." (PMID 34868907, 2021). "However, development of protocols using interleukin 2 (IL-2) has had significant impact on development of cancer immunotherapies." (PMID 34066067, 2021). "Therefore, the production of IL2-enriched membrane vesicles represents a unique opportunity to meet the potential of extracellular vesicles to be used in clinical applications for cancer therapy." (PMID 33579033, 2021). "Here, we conducted a retrospective analysis of 131 unselected stage IV cancer patients with 23 different cancer types who were treated with T-cell-stimulating modalities, hyperthermia, IL-2, and ipilimumab plus nivolumab (0.5 mg/kg and 0.3 mg/kg, respectively)." (PMID 33151369, 2021). "While IL-2 is considered a prototype for γ-chain cytokines and is the quintessential growth factor for T cells, we have opted to use IL-15 instead to combine with IL-12 as a better candidate for cancer immunotherapy for several reasons." (PMID 33182232, 2020).